GLO1 (glyoxalase I)
Diseases named in the same sentence as GLO1 in open-access papers (continued):
Sharing a sentence is not in itself a finding about the gene and the disease.
breast carcinoma (continued). "Application of Glo1 inhibitors for relief of Glo1-linked MDR may be a beneficial adjunct treatment for breast cancer treatment by chemotherapy." (PMID 34790575, 2021). "Therefore, we analyzed for the first time GLO1 gene polymorphism and expression in Egyptian women with breast cancer." (PMID 29321821, 2017). "Amplification of GLO1 may be involved in increasing the risk of breast cancer as well as its progression from localized to advanced." (PMID 29321821, 2017). "SNP of GLO1 was associated with an increased risk of breast cancer." (PMID 29321821, 2017). "GLO1 C332C SNP was associated with overexpression of GLO1 mRNA and higher enzyme activity in breast cancer patients suggesting its role in the development of breast cancer and its progression from localized to advanced." (PMID 29321821, 2017). "Although, GLO1 mRNA expression has been reported in several types of cancers, interestingly, no study has focused on the association between this gene polymorphism and its expression in breast cancer patients in Egypt." (PMID 29321821, 2017). "In clinical chemotherapy of breast cancer, increased expression of Glo1 was associated with decreased patient survival, with hazard ratio (HR) = 1.82 (logrank p < 0.001, n = 683) where upper quartile survival of patients was decreased by 64% with high Glo1 expression." (PMID 34790575, 2021). "Consistent with that idea, Glo1 amplification contributes to the progression of gastric and liver cancers in humans, and a Glo1 polymorphism may influence the gene's expression in breast cancer in Egyptian women." (PMID 30559934, 2018). "Therefore, we hypothese that GLO1 C332C gene polymorphism with the resulting alteration in its expression might represent a promising target for the diagnosis of breast cancer." (PMID 29321821, 2017). "A unique short hairpin RNA (shRNA) was used to effectively and stably suppression GLO1 expression in breast cancer cells." (PMID 40492378, 2025). "We investigated the inhibitory effects of GLO1 depletion on the metastatic capacity of breast cancer cells." (PMID 40492378, 2025). "Taken together, our findings indicate that GLO1 is a promising biomarker of LN metastasis in breast cancer." (PMID 40492378, 2025). "In breast cancer models, MG induction or GLO1 inhibition can achieve significant anticancer effects by activating the MAPK signaling pathway and decreasing the expression of anti-apoptotic proteins (e.g., Bcl-2, MMP-9)." (PMID 40352588, 2025). "Among these hub genes, we screened out GLO1 as a promising biomarker for LN metastasis in breast cancer." (PMID 40492378, 2025). "Curcumin, as a natural inhibitor of GLO1 activity, inhibits the proliferation of breast cancer cells by inducing mitochondrial dysfunction." (PMID 40352588, 2025). "Paracrine orchestration of TME remodeling induced by GLO1 potentiates LN metastasis in breast cancer." (PMID 40492378, 2025). "Molecular analysis identifies a novel RNA‐mediated mechanism of breast cancer pathogenesis, characterised by lncRNA‐dependent suppression of miR‐216a‐5p and subsequent GLO1 dysregulation." (PMID 40344305, 2025). "Extending the resistance axis, proteomic studies identify glyoxalase 1 (Glo1) overexpression as a key contributor to multidrug resistance in breast cancer by detoxifying methylglyoxal and suppressing apoptosis." (PMID 41523619, 2025). "Silencing GLO1 leads to endogenous dicarbonyl stress and enhanced growth and metastasis in breast cancer models." (PMID 38785990, 2024). "Beyond the biochemical evidence, Glo1’s involvement in breast cancer was substantiated by its promotion of cell proliferation, invasion, and migration, coupled with the suppression of apoptosis." (PMID 38785990, 2024). "This upregulation, validated through spectrophotometrical assays and electrophoretic patterns, underscored the potential Glo1’s function in breast cancer." (PMID 38785990, 2024).
breast carcinoma (continued). "The complex nature of Glo1’s activity in breast cancer is highlighted by its dualistic role, which can act as a suppressor or a promoter depending on the situation." (PMID 38785990, 2024). "Many human cancers have been shown to have an increased Glo1 copy number; breast cancer, sarcomas, and non-small cell lung cancer have the greatest frequencies of these tumors." (PMID 38785990, 2024). "In conclusion, the saga of Glo1 in breast cancer unfolds as a multifaceted narrative, weaving through tumorigenesis, drug resistance, prognostic challenges, and metastasis." (PMID 38785990, 2024). "The study, conducted on samples drawn from 20 women between 1999 and 2000, revealed a significant upregulation of Glo1 in tissues and cells of human breast cancer." (PMID 38785990, 2024). "Determining MGO concentrations becomes imperative when applying Glo1 inhibitors, highlighting the importance of context-dependent responses in unraveling the complexities of breast cancer biology." (PMID 38785990, 2024). "High expression levels of both Glo1 and PKCλ were associated with a worse prognosis in patients with stage III–IV breast cancer." (PMID 38785990, 2024). "A recent study investigating the impact of glyoxalase 1 (GLO1) silencing on breast cancer cells adds another layer to our understanding of cancer biology." (PMID 38785990, 2024). "We have shown that HSP90 is glycated on several arginine residues in stably GLO1-depleted breast cancer cells, which impeded the good functioning of the Hippo tumor suppressor pathway." (PMID 37408249, 2023). "We previously used GLO1 stable depletion strategy in MDA-MB-231 TNBC breast cancer cells to induce endogenous MG accumulation and the formation of glycated adducts resulting in cellular dysfunction, hereafter mentioned as MG stress." (PMID 36998085, 2023). "CDH1, CST6, MUC1 and SCNN1A genes, all reported to be aberrantly hypermethylated in breast cancer, were down-regulated in both MDA-MB-231 and Hs578T GLO1-depleted breast cancer cells when compared with control." (PMID 36998085, 2023). "GLO1-depleted breast cancer cells showed elevated expression of DNMT3B methyltransferase and significant loss of metastasis-related tumor suppressor genes, as assessed using integrated analysis of methylome and transcriptome data." (PMID 36998085, 2023). "In a study of 225 different types of human tumors, increased Glo1 copy number was discovered in 8% of tumors, with the highest prevalence of Glo1 amplification in breast cancer (22%), followed by sarcomas (17%) and non-small cell lung cancer (11%)." (PMID 35898868, 2022). "In our study of 225 human tumors of different types, the highest prevalence of GLO1 copy number increase was in breast cancer (22%), sarcomas (17%), and non-small cell lung cancer (NSCLC) (11%)." (PMID 35269594, 2022). "Silencing of Glo1, bearing a higher level of MGO, promoted tumor growth and metastasis in vivo and Glo1-depleted breast cancer cells induced a significant increase in pulmonary tumor burden." (PMID 35898868, 2022). "Recent studies on the mechanism of drug resistance of breast cancer have found that Glo1 inhibitors can reserve drug resistance of tumor cells." (PMID 35898868, 2022). "A consistent enhanced of Glo1 expression was observed either at mRNA or protein level in human breast cancer tissues parallel with pair-matched normal tissue, providing evidence for a potential role of this enzyme in breast cancer." (PMID 35898868, 2022). "Samples were drawn in the period from 1999 to 2000 of 20 women and Glo1 was significantly upregulated in human breast cancer cells and tissues, as shown by both spectrophotometrical assay and electrophoretic pattern compared with normal counterparts." (PMID 35898868, 2022). "Previous research has shown that the expression of Glo1 is upregulated in a variety of human malignancies, including melanoma, gastric cancer, pancreatic cancer, breast cancer, renal cancer, prostate cancer." (PMID 35898868, 2022).
breast carcinoma (continued). "Amplification of Glo1 gene has been found to be a frequent genetic event in breast cancer, sarcoma, non-small-cell lung cancer (NSCLC) and, more recently, in HCC." (PMID 33869040, 2021). "High expression of Glo1 contributes to multidrug resistance by shielding the spliceosome from MG modification and decreasing survival in the chemotherapy of breast cancer." (PMID 34790575, 2021). "Particularly, our results show that the activity levels of GLO1 in breast carcinoma, significantly higher than in pair-matched normal tissues as it was previously reported in several human cancers." (PMID 35223406, 2021). "Our findings implicate expression of Glo1 in human breast cancer as a factor with major impact on patient survival." (PMID 34790575, 2021). "Remarkable genes coding for ECM components and ECM regulators, the expression of which is significantly modulated in GLO1-depleted MDA-MB-231 breast cancer cells." (PMID 30674353, 2019). "In this study, we used RNA sequencing analysis to investigate gene-expression profiling of GLO1-depleted breast cancer cells and we validated the regulated expression of selected genes of interest by RT-qPCR." (PMID 30674353, 2019). "We have further demonstrated that MEK/ERK-sustained activation in GLO1-depleted cells notably occurs through the down-regulation of dual specificity phosphate 5 (DUSP5) phosphatase expression upon MG stress in breast cancer cells." (PMID 30674353, 2019). "Based on these data, we sought to corroborate the functional relevance of MG-mediated MEK/ERK hyperactivation with the enhanced migratory ability of GLO1-depleted breast cancer cells." (PMID 30674353, 2019). "We showed that sustained MEK/ERK activation in GLO1-depleted cells notably occurred through the down-regulation of the expression of dual specificity phosphatases in MG-stressed breast cancer cells." (PMID 30674353, 2019). "As such, GLO1 is a potential therapeutic target for treatment ALDH1-positive CSCs in basal like breast cancers." (PMID 30559934, 2018). "In the present study, we focused on the role of GLO1 in ALDH1-positive CSCs in basal-like tumors using genomics datasets for human breast cancer." (PMID 30559934, 2018). "We initially compared Glo1 expression in normal (n = 61) and cancer tissues (n = 532) from breast cancer patients using the TCGA dataset." (PMID 30559934, 2018). "Despite a lack of correlation between Glo1 and ALDH1A3 expression, a major population of patients with basal-like breast cancers highly expressed both Glo1 and ALDH1A3 (n = 70 of 199)." (PMID 30559934, 2018). "We therefore conclude that GLO1 is a potential therapeutic target for treatment of basal-like breast cancers." (PMID 30559934, 2018). "We therefore investigated GLO1 expression in breast cancer subtypes and its function in ALDH1-positive CSCs." (PMID 30559934, 2018). "Comparison of Glo1 expression in subtypes of breast cancer and normal tissues derived from the same patients in the TCGA dataset revealed that Glo1 expression was significantly higher in basal-like cancers than normal tissues." (PMID 30559934, 2018). "We observed that in addition to breast cancer, Glo1 expression is also higher colon and ovarian cancers than in normal tissues." (PMID 30559934, 2018). "GLO1 expression is reportedly high in HER2 breast cancer tissues and cell lines and is stimulated by HER2 signaling." (PMID 30559934, 2018). "This suggests analysis of GLO1 function in CSCs in breast cancer subtypes other than the basal-like type is needed." (PMID 30559934, 2018). "In the present study, we used human breast cancer genomics dataset analysis to show that GLO1 expression is elevated in human basal-like breast cancer tissues, and that inhibition of GLO1 suppresses cell viability and tumor-sphere formation by ALDH1high cells." (PMID 30559934, 2018).
breast carcinoma (continued). "In this study, we found that GLO1 gene expression correlates with neoplasm histologic grade (χ2test, p = 0.002) and is elevated in human basal-like breast cancer tissues." (PMID 30559934, 2018). "This is consistent with the earlier report that GLO1 expression at protein level correlates with tumor grade in breast cancer specimen." (PMID 30559934, 2018). "High levels of GLO1 mRNA and protein expression have been observed in several cancers, including breast cancer." (PMID 30559934, 2018). "Although the expression of GLO1 has been reported in some human cancers, very few studies were performed in selected population on GLO1 expression in breast cancer." (PMID 29321821, 2017). "GLO1 mRNA expression and enzyme activity were significantly higher in breast cancer patients compared to controls and they were much higher in the advanced stages of the disease (P < 0.001)." (PMID 29321821, 2017). "Regarding the serum activity of GLO1, breast cancer patients had higher serum GLO1 activity (230±60) compared to controls (150±41; p < 0.001)." (PMID 29321821, 2017). "Patients with advanced breast cancer (225±56) had significantly higher GLO1 activity not only compared to controls, but also compared to localized breast cancer (200±50; P < 0.001)." (PMID 29321821, 2017). "Using cancer cells stably depleted for GLO1 as a model of high endogenous MG, we demonstrated in vivo the pro-tumorigenic and pro-metastatic roles of dicarbonyl stress in breast cancer." (PMID 28117708, 2017). "In our hands, the use of a stably depleted GLO1 xenograft tumor model in vivo allowed the demonstration of the pro-tumorigenic and pro-metastatic role of endogenous MG accumulation in breast cancer cells." (PMID 28117708, 2017). "When stratified by tumor stage, the frequency of the homozygous mutant genotype AA of GLO1, was significantly higher among advanced stages of breast cancer compared with less invasive tumors (p = 0.002)." (PMID 29321821, 2017). "Increased GLO1 copy number was previously found in other human tumours where the highest prevalence was in breast cancer, small cell lung cancer and non-small cell lung cancer." (PMID 29100361, 2017). "GLO1 mRNA expression was presented as mean±SD, it was higher in breast cancer patients (3.1±0.5) compared to controls (1±0.3)." (PMID 29321821, 2017). "In agreement with us, higher GLO1 activity was observed in cancerous tissues, such as breast cancer, kidney tumors and prostatic cancer." (PMID 29321821, 2017). "GLO1 C332C gene polymorphism was analyzed by PCR-RFLP in 100 healthy controls and 200 patients with breast cancer (100 patients with stage I & II and 100 patients with stage III & IV)." (PMID 29321821, 2017). "Using stably depleted GLO1 xenografts in vivo, we have also demonstrated the pro-tumorigenic and pro-metastatic role of endogenous MG accumulation in breast cancer cells." (PMID 27759563, 2016). "In the present study, we knocked-down GLO1 in the tumorigenic epithelial human breast cancer cell line MCF-7 and overexpressed it in epithelial human embryonic kidney HEK 293 cells." (PMID 27999356, 2016). "Following the assessment of GLO1-silencing impact on tumor growth, we next evaluated the metastatic behavior of GLO1-depleted breast cancer cells." (PMID 27759563, 2016). "After we have validated exogenous MG effects, we used 2 strategies in order to assess high endogenous MG impact on YAP in breast cancer cells: (a) inhibition of GLO1, the main MG-detoxifying enzyme and (b) high-glucose culture condition." (PMID 27759563, 2016). "For this purpose, we used two shRNAs specifically directed against GLO1 to stably induce high endogenous MG stress in MDA-MB-231 breast cancer cells." (PMID 27759563, 2016). "In a recent proteomic study, Glo-1 expression has been shown to be positively correlated with high tumor grade in breast cancer." (PMID 24978626, 2014).
breast carcinoma (continued). "Using breast cancer cell lines, we substantiated these clinical observations by showing that, in contrast to triple positive, triple negative cells induced Glo-1 expression and activity in response to MG treatment." (PMID 24978626, 2014). "This study offers new profound insights into the LN metastasis of breast cancer cells, investigate the remodeling process of the LN microenvironment, and elucidate the role of GLO1 as a promising biomarker and therapeutic target for improving the treatment outcomes of patients with breast cancer." (PMID 40492378, 2025). "Of interest, GLO1 inhibitors have been shown to reverse the sensitivity of tamoxifen-resistant breast cancer cells, revealing that GLO1 may be a biomarker for predicting the efficacy of endocrine therapies and a target for overcoming treatment resistance." (PMID 40352588, 2025). "This study offers novel perspectives on the microenvironment remodeling of breast cancer LN metastases, suggesting that GLO1 might be a promising therapeutic target." (PMID 40492378, 2025). "Our results showed that GLO1 depletion and pharmacological inhibition could hinder proliferative and metastatic capacities of breast cancer cells." (PMID 40492378, 2025). "For instance, in a mouse xenograft model, GLO1-depleted breast cancers showed increased tumorigenic and metastatic potential and similarly, increased aggressiveness of colorectal cancer patients’ cancer cells inversely correlated with GLO1 activity." (PMID 41100182, 2025). "This study concluded that GLO-1 and PKCλ could serve as potentially effective therapeutic targets for the treatment of late-stage human breast cancer." (PMID 40727469, 2025). "Collectively, our study offers novel perspectives on the microenvironment remodeling of LN metastasis in breast cancer, suggesting that GLO1 might be a key target for LN metastasis in breast cancer." (PMID 40492378, 2025). "Collectively, the study offers novel perspectives on the microenvironment remodeling of breast cancer LN metastases, suggesting that GLO1 may be a promising therapeutic target." (PMID 40492378, 2025). "Furthermore, a co‐immunoprecipitation (co‐IP) assay confirmed that endogenous GSH was enriched in the protein complex immunoprecipitated using the GLO1 antibody in breast cancer cell lines." (PMID 40492378, 2025). "Glo1 overexpression was found to be independently related to lower overall survival and recurrence-free survival, which highlights its critical involvement in the course of breast cancer." (PMID 38785990, 2024). "In breast cancer, glyoxalase I (GLO1) levels are regulated by estrogens." (PMID 38785550, 2024). "Recent reports propose a cooperative involvement of Glo1 and PKCλ in breast cancer progression." (PMID 38785990, 2024). "We have shown that breast cancer cells stably silenced for glyoxalase 1 (GLO1), the main MG detoxifying enzyme, showed enhanced tumor growth and metastasis development, which were facilitated by heat shock protein 90 (HSP90) glycation and inhibition of the Hippo tumor suppressor pathway." (PMID 37408249, 2023). "Furthermore, upon GLO1 depletion, breast cancer cells displayed a distinctive MG stress gene signature, which highlighted major ECM remodeling and activation of migratory and invasion signaling pathways." (PMID 37408249, 2023). "Therefore, Glo1 is involved in the regulation of tumorigenesis, proliferation, migration and survival in breast cancer." (PMID 35898868, 2022). "According to a recent report, in patients with stage III−IV breast cancer, Glo1 and PKCλ may be cooperatively involved in cancer progression and patients with high Glo1 and PKCλ expression had worse prognosis." (PMID 35898868, 2022). "measured Glo1 specific activity in breast carcinoma and normal mammary gland tissue." (PMID 35898868, 2022). "Moreover, knockdown of Glo1 suppressed invasion and migration and promoted apoptosis of breast cancer cells in vitro." (PMID 35898868, 2022).